FOXO1 (forkhead box O1)
Diseases named in the same sentence as FOXO1 in open-access papers (continued):
Sharing a sentence is not in itself a finding about the gene and the disease.
tumor (continued). "Hippo signaling is suppressed in alveolar RMS cell lines and tumors, and genetically inhibiting the Hippo/MST signaling by knocking out kinases MST1 and MST2 (Stk4, Stk3), led to more rapid Pax3::Foxo1 tumor onset and higher penetrance." (PMID 40599857, 2025). "In contrast, FOXO1 was consistently downregulated, highlighting its potential as a tumor suppressor." (PMID 40396172, 2025). "In the zebrafish PAX3::FOXO1 tumor model, the effect of many promoters/restricted cell lineages was investigated to understand transformation capacity on a broader scale." (PMID 40599857, 2025). "VEGFA was, as expected, elevated in GPR65 KO compared with m.CR tumor cells and was significantly diminished after FOXO1 KO." (PMID 39998425, 2025). "This identified Foxo1 among the top three TFs upregulated in GPR65 KO compared with m.CR tumor cells." (PMID 39998425, 2025). "A transcription factor FOXO1 functions as a tumor suppressor and is inactivated via phosphorylation, resulting in activation of several proteins, including the phosphoinositide 3 kinase (PI3K)/AKT pathway." (PMID 40486871, 2025). "It has been shown that it can interact with the FOXO1 gene, where reduced activity promotes the formation of tumor spheres and increases the viability of tumor cells and their ability to proliferate, promoting disease progression." (PMID 40563399, 2025). "Yet, the upstream cues (AMPK versus AKT versus eicosanoid signalling), the dominant FoxO isoform (FoxO1 versus FoxO3), and the pathological drivers (hyperglycemia, inflammation, tumor burden, hyperlipidemia) differ." (PMID 40861274, 2025). "As a tumor suppressor gene, FOXO1 was shown to inhibit the proliferation and clonogenic potential of tumor cells." (PMID 41203613, 2025). "Future studies quantifying FOXO1 protein levels or its nuclear localization are needed to definitively establish its role in the anti-tumor effects observed in vivo." (PMID 41458598, 2025). "Phagocytosis regulators exhibited differential expression across various female-specific cancers, with key genes such as CD47 and FOXO1 playing significant roles in modulating tumor progression." (PMID 40396172, 2025). "The apparently contradictory effects of SIRT1 in NSCLC reflect context-specific routing through HNRNPD/PGC-1α-driven pro-angiogenic versus FOXO1-dependent tumor-suppressive networks." (PMID 41425553, 2025). "PE supplementation prominently restored the levels of p-Akt, p-FoxO1, and p-NF-κB p65 altered by the tumor." (PMID 40136406, 2025). "The overexpression of Sirt1 reduces the protein level of FOXO1, resulting in the inhibition of androgen production in U87 cells, consequently suppressing tumor cell proliferation and invasion." (PMID 40075208, 2025). "This latter finding can be explained by the very low expression of Pax3::Foxo1 in these Pax7 lineage tumours, resulting in an inadequate amount of Pax3::Foxo1 to modulate the epigenetic landscape in this setting." (PMID 39812007, 2025). "As only one tumour arose in the setting of Pax3::Foxo1 directed to the Myf5 lineage, which is often embryonic lethal, the usual impact of Pax3::Foxo1 on DNA methylation in this lineage is unclear." (PMID 39812007, 2025). "Inhibition of FOXO1, the main regulatory factor of T cell memory imprints in CAR-T cells, will lead to cell exhaustion and reduce anti-tumor response, while increasing FOXO1 expression will enhance anti-tumor ability and increase mitochondrial mass." (PMID 40469307, 2025). "In androgen-deprived prostate cancer, the activation of the FOXO-1/Sirt1 axis promotes tumor progression." (PMID 40075208, 2025). "While patients with nonmetastatic localized RMS tumors have good to excellent prognoses depending on tumor site/size, age, and FOXO1 fusion status, children with disseminated disease have a poor prognosis with OS ~ 30%." (PMID 38371622, 2024). "Significantly higher expression of PTEN (p < 0.0001) and FOXO1 (p < 0.0001) were observed in normal tissue compared to tumor tissue." (PMID 38891994, 2024).
tumor (continued). "Our clinical analysis of SKCM and TNBC ICI cohorts revealed a correlation between increased FOXO1 expression and immunotherapy resistance, suggesting the potential immunosuppressive role of FOXO1 in tumour immunotherapy." (PMID 38899748, 2024). "To compare the effect of TCF7, ID3 and FOXO1 overexpression in vivo we treated OVCAR-3 tumour-bearing mice with Lewis Y CAR T cells." (PMID 38600376, 2024). "It was found that changes in FOXO1 gene expression depended on patient age, with higher expressions observed in the tumor tissue of patients above the median age of the studied group (68 years) compared to the younger group." (PMID 38891994, 2024). "Higher FOXO1 expression was also noted in tumor tissue originating from the rectum compared to tumors located within the colon." (PMID 38891994, 2024). "The inhibition of FOXO1, a critical molecule in immune resistance, can induce immune activation or promote tumour cell death, thereby enhancing the efficacy of immunotherapy." (PMID 38899748, 2024). "Collectively, our data suggest that overexpression of FOXO1-ADA in CAR T cells contributes to enhanced in vivo anti-tumour activity by promoting T cell polyfunctionality, proliferation and mitochondrial biogenesis to support effector functions." (PMID 38600376, 2024). "A HepG2 cell–transplanted tumor model was established in nude mice, and CK inhibited the growth of transplanted tumors in nude mice, p-FOXO1 was decreased in tumor tissues, and SLC7A11 and GPX4 expressions were also down-regulated after CK treatment." (PMID 38664638, 2024). "For evaluation of entinostat monotherapy, models CTG-1008 and CTG-1916 had no single agent activity in line with previously-published studies showing that PAX3::FOXO1 is dispensable for tumor maintenance in the short term." (PMID 39147820, 2024). "A study found that the CSF1 modulation of TAM and tumor progression is affected by the transcription factor forkhead box protein O1 (FOXO1)." (PMID 39201328, 2024). "Tumour cells undergo autophagy during oxidative stress or serum starvation, and this process is regulated by acetylation of FoxO1 (Ac‐FoxO1)." (PMID 38149787, 2024). "Integrating candidate MRs, genes negatively correlated with tumour cell MOMP activity, and CRISPR screening, FOXO1 emerged as the most significant MR associated with the maintenance of immunotherapy resistance." (PMID 38899748, 2024). "In cellular experiments involving seven cell lines from five different tumours treated with a FOXO1 inhibitor (1 μM, 48 h), FOXO1 expression was variably suppressed." (PMID 38899748, 2024). "ROS regulates the function of FOXO1 through upstream signaling that activates ROS-sensitive FOXOs to maintain cellular homeostasis, acting as tumor suppressors that control the cell cycle." (PMID 38436783, 2024). "Phenotypic analysis of FOXO1-overexpressing CAR T cells following co-culture with tumour cells revealed a similar expression of PD-1 and TIM3, but reduced expression of CD39 relative to control CAR T cells." (PMID 38600376, 2024). "Despite PAX3::FOXO1 being dispensable in the short turn to tumor cell growth, PAX3::FOXO1 is nonetheless critical to mediate a G2-specific, Survivin/IAP-mediated process of chemotherapy resistance called cell cycle checkpoint adaptation." (PMID 39147820, 2024). "In 20 paired tumor and normal breast tissues, the levels of circCNIH4 and FOXO1 were lower in tumor than normal tissues." (PMID 39135158, 2024). "FOXO1 is a transcription factor and potential tumor suppressor that is negatively regulated downstream of PI3K-PKB/AKT signaling." (PMID 38519029, 2024). "Increasing evidence has shown that FOXO1 can also play a role as a tumor suppressor; it inhibits the proliferation, migration, and invasion of tumor cells, and promotes the apoptosis of tumor cells." (PMID 38664638, 2024). "Both AMPKα1 and FOXO1 were also described as tumor suppressors because of their inhibitory effect on tumor growth." (PMID 39611157, 2024).
tumor (continued). "The analysis identified significantly higher PTEN and FOXO1 expressions in normal tissue compared to tumor tissue in both the colon and rectum." (PMID 38891994, 2024). "FOXO1 is also considered a tumor suppressor because it regulates the transcription of genes that play important roles in cell cycle arrest and apoptosis induction." (PMID 38519029, 2024). "In the context of serial co-cultures with OVCAR-3 or MCF7 tumour cells, FOXO1 overexpression led to a significant increase in the recovery of CD8+ and CD4+ CAR T cells and similar levels of IFNγ and TNF production compared with control CAR T cells." (PMID 38600376, 2024). "FoxO1, a transcription factor, has been identified as a tumour suppressor in a variety of human cancers." (PMID 39153212, 2024). "Of note, intratumoral FOXO1OE cells did not have a canonical memory-like phenotype but were enriched in a FOXO1OE transcriptomic signature derived from bulk RNA-seq studies, suggesting that exogenous FOXO1 remains active in the tumour microenvironment." (PMID 38600391, 2024). "In summary, we have shown for the first time that Zn intake negatively regulates antitumor immune response by FOXO1-mediated regulation of Treg cell differentiation and function and also suppresses α-PD-1 tumor immune checkpoint therapy response." (PMID 39247196, 2024). "Overexpression of wild-type FOXO1 in human CAR T cells led to significantly enhanced tumour regression in mice." (PMID 38600376, 2024). "In this model, the human VGLL2::NCOA2 coding sequence was incorporated into the zebrafish genome under the ubiquitous CMV promoter using a similar approach to the PAX3::FOXO1-driven zebrafish tumor model." (PMID 38916046, 2024). "Akt promotes glucose metabolism in tumor cells by ubiquitinating and degrading FoxO1 through protease phosphorylation." (PMID 39584783, 2024). "Two recent studies found that direct overexpression of FOXO1 in CAR-T cells improves anti-tumour efficacy." (PMID 39399500, 2024). "Studies have shown that FOXO1 activity is modulated by phosphorylation, methylation, acetylation, and ubiquitination, affecting its tumor-suppressive or oncogenic functions in lung carcinogenesis." (PMID 39201328, 2024). "Primarily recognised as a tumour suppressor, FOXO1 exerts its tumour‐suppressive influence by regulating downstream PI3K/AKT signalling and attenuating the activities of the MYC and WNT signalling pathways." (PMID 38899748, 2024). "Isolated tumor cells with lower Pax3::Foxo1 expression had a higher oncogenic capability in allograft models and more migratory potential in vitro, a phenomenon that is also seen for the EWSR1::FLI1 fusion in Ewing sarcoma." (PMID 38916046, 2024). "These images show that the expression of FOXO1 was higher in normaltissues compared with the tumor tissue in these cancers." (PMID 38716982, 2024). "Theaim of this study was to acquire FOXO1 expression patterns in diverse tumors,investigate the correlation between FOXO1 expression and tumor prognosis, anduncover the potential mechanisms of FOXO1 in various malignancies." (PMID 38716982, 2024). "FOXO1i and FOXO1KO cells also exhibited attenuated killing and/or cytokine secretion after tumour challenge, consistent with a model in which FOXO1 restrains exhaustion and/or terminal differentiation in human T cells, similar to reports in mice." (PMID 38600391, 2024). "CAR T cells that overexpressed FOXO1 retained their function, memory potential and metabolic fitness in settings of chronic stimulation, and exhibited enhanced persistence and tumour control in vivo." (PMID 38600391, 2024). "Next-generation sequencing revealed six tumor-specific mutated genes (IGH/BCL6, TNFAIP3, PRDM1, CREBBP, DTX1, and FOXO1)." (PMID 37884941, 2023). "KAT7, for example, inhibits tumor cell proliferation and invasion by acetylating H4K5 at promoters of FOXO1 and FOXO3a genes, and HDAC5 loss increased H3K27-ac acetylation and circumvented oncogene-related cell cycle repression." (PMID 37789275, 2023).
tumor (continued). "In contrast, genetic and pharmacological inactivation of FOXO1 produces a tumour suppressive effect by means of caspase-induced cell death in pre-BCR- and pre-BCR+ BCP-ALL cells via CCND3 downregulation." (PMID 37275916, 2023). "The results indicated that FOXO1 significantly promoted tumor invasiveness, migration, and proliferation in OV cell lines, though the underlying mechanism needs further investigation." (PMID 37120633, 2023). "Activation of the PI3K/AKT/mTOR pathway results in phosphorylation of FOXO1 and prevents it from entering the nucleus, providing a mechanistic explanation for the enhanced anti-tumor effect of HDAC inhibitor and PI3K/mTOR inhibitor combination therapy." (PMID 37568705, 2023). "Regarding HCC, Foxo1 shows tumor suppressor activity by resisting precancerous oxidative stress and inhibiting cell migration and invasion." (PMID 37298191, 2023). "Three-fourths of the relapses (n = 28; 75%) occurred in patients with primary tumours at unfavourable sites and 12 (36%) amongst these were FOXO1 positive (P3F and P7F in 6 each)." (PMID 37138963, 2023). "The test results showed that the tumor-specific mutations in this sample were as follows: BCL6, TNFAIP3, PRDM1, CREBBP, DTX1, and FOXO1." (PMID 37884941, 2023). "The current ARTS1431 risk stratification, which employs FOXO1 status in lieu of histology has shifted LR (B) and FOXO1 positive tumours under IR tumours." (PMID 37138963, 2023). "FOXO1 has tumor-suppressive properties and induces apoptosis by suppressing Bcl-2 and promoting Bax activity." (PMID 37438760, 2023). "Contextually, decreased protein levels of Cyld and Foxo1 tumor suppressors were detected, and the in vitro results indicated miR-182 mediated Cyld and Foxo1 regulation." (PMID 37298191, 2023). "Rho GTPases, including RHOB, can regulate several pathways related to signal transduction, cell adhesion, tumor cell invasion, and cell division, warranting further future examination of both FOXO1 and RHOB in H3K27M DMGs." (PMID 37094128, 2023). "A very potent transcriptional activator, FOXO-1, induces the expression of genes involved in cell cycle arrest, apoptosis, DNA repair, and tumor suppression." (PMID 36850982, 2023). "An in vitro assay on HepG2 cells confirmed Cyld and Foxo1, both tumor-suppressor, as miR-182-5p target genes." (PMID 37298191, 2023). "During the investigations, the results illustrated an association between miR-182 overexpression and the suppression of FOXO1 tumor suppressor." (PMID 37438760, 2023). "It was also shown that LINC0108 upregulation, a member of the long noncoding RNAs, increased FOXO1 expression followed by enhancement of the tumor suppressive effects of FOXO1 in HCC cells by sponging miR-182-5p." (PMID 37438760, 2023). "FOXO1 is considered a key tumor suppressor in cancer, including PCa, and was found to be markedly downregulated in PCa samples." (PMID 38139289, 2023). "The in vivo findings in ectopic xenograft mouse models further confirmed that the circHERC1 overexpression resulted in larger tumor volumes and stronger fluorescence than the control, while this promoting effect was attenuated by FOXO1 knockdown." (PMID 37932766, 2023). "FOXO1 belongs to the forkhead transcription factor family, which can act as a tumor suppressor to regulate the expression of various genes to control important processes such as cell proliferation, survival and resistance to oxidative stress." (PMID 37640964, 2023). "The acetylated FoxO1 binds to Atg7 in the cytosol, leading to the induction of autophagy, autophagic cell death, and tumor suppression in vitro and in vivo." (PMID 37762548, 2023). "We also observed an increased expression of FOXO1 with BACE1 inhibition, associated with reduced cell proliferation and reduced tumor volume." (PMID 38201438, 2023). "IHC of tissue microarrays indicated that FOXO1 expression staining was mainly located at the cytoplasm of tumor cells." (PMID 37120633, 2023).
tumor (continued). "Two cases harbored only the FOXO1 fusion at primary tumor and subsequently acquired up to 4 new alterations at relapse." (PMID 37730754, 2023). "A prior study highlighted that the deletion of FOXO1 in adult mice heightens tumor incidence, while its activation halts the cell cycle and induces apoptosis in tumor cells." (PMID 37987362, 2023). "As tumor suppressors, FOXO1 and FOXO3 were suggested to be downstream mediators of CRC cancer health disparities." (PMID 37081981, 2023). "FOXO1 is a tumor suppressor and its downregulation leads to promoting tumorigenesis by favoring resistance to stress, proliferation, and increased cellular survival." (PMID 37500691, 2023). "In BL, although the PI3K-AKT pathway is activated, there are abundant nuclear FOXO1 proteins which promote tumor growth and survival, presenting as an important oncogenic event in B-cell lymphomagenesis." (PMID 36675119, 2023). "FOXO1 acts as a tumor suppressor in OS suppressed tumor progression by downregulating the Wnt/β-catenin pathway." (PMID 37284323, 2023). "CRISPR/Cas9-mediated FOXO1 ablation strongly restricted tumour growth, demonstrating FOXO1 as a key driver of BL." (PMID 37275916, 2023). "Amongst the relapses that occurred in favourable site – primary tumours (n = 7), 5 (71%) were FOXO1 positive (P3F: 3; P7F: 2)." (PMID 37138963, 2023). "FOXO1 is a well-known tumor suppressor, but recent studies also reported tumor-promoting functions of the TF for different tumor entities." (PMID 36817488, 2023). "The distribution of FOXO1 positive tumours across favourable (12/42) and unfavourable (27/98) was similar (p = 0.90)." (PMID 37138963, 2023). "In the subset of favourable tumours however, presence of FOXO1 fusions portended an inferior survival trending towards statistical significance (p = 0.063)." (PMID 37138963, 2023). "In the subset of favourable site tumours however, presence of FOXO1 fusions conferred an inferior survival (p = 0.063)." (PMID 37138963, 2023). "The mRNA and protein expression of SIRT1 and NOX4 was significantly downregulated in the LLC tumor groups compared to the control group, as well as FOXO1 and FOXO3a in vitro." (PMID 37190306, 2023). "In contrast, in an aggressive CLL mouse model, FOXO1 was shown to be a driver of disease through induction of IGF1R in PI3K-inhibitor-resistant SLO tumours: this was attenuated by pharmacological FOXO1 inhibition (AS1842856)." (PMID 37275916, 2023). "The proportion of nodal disease was comparable across FOXO1 fusion status (48.7% versus 33.6%; p = 0.10) and the site of the tumour (33.3% versus 39.8%; p = 0.47)." (PMID 37138963, 2023). "Quercetin and leucine alone have been shown to downregulate the FoxO1/MuRF1/Atrogin-1 pathway and decrease muscle wasting in trichostatin-treated tumor-bearing mice and in the C2C12 muscle cell model, respectively." (PMID 37699022, 2023). "FOXO1 is a transcription factor for tumor suppressor, which is inactivated in tumor cells and acts as a target of the AR/ERβ pathway." (PMID 36732762, 2023). "FOXO1 is also a transcriptional regulator of MHC-II expression and mediates an anti-tumour effect in tumour-associated macrophages." (PMID 37637416, 2023). "Of note, in combined FOXO1/3- knockout or FOXO1/4- knockout animals, tumor incidence was slightly increased." (PMID 37891184, 2023). "Firstly, we found the lower FOXO1 expression in tumor groups compared with normal controls in GSE15852 and GSE10797." (PMID 35800988, 2022). "Increased expression of SIRT1, FoxO1 and FoxO3a in the 67NR group confirms our results which related to the metastatic character of the tumor." (PMID 36142156, 2022). "Many studies have reported that FOXO1 has anti-tumor effects on a variety of tumors, including hematological tumors, digestive system tumors, prostate tumors and breast tumors." (PMID 36290822, 2022).